GLS (glutaminase)
Diseases named in the same sentence as GLS in open-access papers (continued):
Sharing a sentence is not in itself a finding about the gene and the disease.
tumor (continued). "Genetic approaches using RNA interference techniques and CRISPR/Cas9 technology demonstrated that the loss of ERK5 function led to increased protein levels of GLS isoforms (KGA/GAC) and a concomitant increase in their activity in tumor cells." (PMID 38542254, 2024). "Co-treatment of glutor and glutaminase inhibitor CB-839 has shown greater potency at inhibiting tumor cell growth in the presence of high glucose and glutamine levels." (PMID 39329757, 2024). "Glutaminolysis, a metabolic process prevalent in all proliferating cells, especially in tumor cells, involves conversion of glutamine to glutamate, catalyzed by Glutaminase (GLS)." (PMID 39252939, 2024). "Glutaminase activity is essential for the production of glutamate, which can be further utilized in various metabolic pathways to support tumor growth." (PMID 39170262, 2024). "This interaction enhances GLS gene expression, which not only leads to elevated mitochondrial glutaminase activity but also to increased dependence of tumor cells on glutamine-mediated anaplerosis." (PMID 38172980, 2024). "GLS, a key enzyme of glutamine metabolism, is overexpressed in several tumour cells, and targeting GLS significantly inhibits tumour cell proliferation." (PMID 39663596, 2024). "For TNBC that is specifically “glutamine-addicted”, tumor cells exhibit elevated levels of ASCT2 as well as GLS." (PMID 39107856, 2024). "Based on the in-depth understanding of glutamine metabolic pathways, the development of molecular drugs that specifically target glutaminase or transporters offers innovative strategies to combat tumor growth and curb tumor progression." (PMID 38172980, 2024). "Hypoxic conditions induced the reductive metabolism of glutaminase in tumor cells, resulting in the transcriptional activation of GLS via HIF-1α upregulation." (PMID 38459595, 2024). "TNBC cells further metabolize the glutamine through the glutamine transporter (ASCT2) and glutaminase (GLS1) axes, which, in turn, promote mitochondrial activity and tumour progression." (PMID 39690134, 2024). "CsA and a glutaminase inhibitor combination therapy significantly retard tumor progression in NSCLC patient-derived xenograft (PDX) models with NRF2 hyperactivation." (PMID 38830868, 2024). "Within the tumor microenvironment (i.e. replete and deplete oxygen and nutrient supply) GLS activity is possibly finely tuned through splicing mechanism for adaption." (PMID 38488852, 2024). "By the year 2000, specific gene suppression of glutaminase (GLS) became a promising strategy for effectively impeding tumor cell growth." (PMID 38459595, 2024). "Metabolic requirements in tumor metastasis: CB-839 is a GLS inhibitor and reduces the conversion of glutamine to glutamate." (PMID 38921453, 2024). "In parallel, we treated mice bearing HepG2 xenografts with the GLS inhibitor CB-839 and then took the tumor tissues for transcriptomic sequencing." (PMID 38802351, 2024). "The expression of the antisense lncRNA of glutaminase (GLS-AS) is lower in PC than that of non-tumor adjacent tissues." (PMID 38184562, 2024). "Aside from arginine metabolic inhibitors, glutaminase inhibitors have the potential to target both immunosuppressive TAMs and the tumor, as glutaminolysis is essential for both cells." (PMID 38226622, 2024). "RT-qPCR and IHC indicated that the expression of GLS, NOX1, HOXC6, TNNT1 and PLA2G12B were up-regulated in tumor tissues, compared with those in normal tissues, and all of GLS, HOXC6, NOX1 and PLA2G12B were closely related with patient survival." (PMID 37333810, 2023). "GLS loss or GLS-specific inhibitor bis-2-(5-phenylacetamido-1,3,4-thiadiazol-2-yl)ethyl sulfide (BPTES) attenuates tumor progression and prolonged survival in Myc-driven HCC mouse model." (PMID 37635935, 2023). "In all other plurimetabolic PDX, however, MCT4 and GLS were expressed mainly by different tumor cells which were located in the same spatial region of the tumor." (PMID 36925926, 2023).
tumor (continued). "The results revealed that LIAS, DLAT, PDHA1, and CDKN2A were significantly upregulated in LUAD tumors compared to normal tissues, while ATP7B, SLC31A1, FDX1, MTF1, and GLS were significantly downregulated in tumor tissues." (PMID 36983664, 2023). "Glutamate, the initial product of glutamine catabolism catalysed by glutaminase enzyme fuels the glucose-independent TCA cycle in a nutrient deprived tumour microenvironment." (PMID 37623834, 2023). "Through the knock-down of GLS expression, it was found that GLS expression was strongly relevant to the growth and metastasis of tumor." (PMID 37664031, 2023). "Glutaminase (GLS), converting glutamine to glutamate, was downregulated in tumor cells compared with Macro_APOE/CTSZ, in CRC samples." (PMID 36587392, 2023). "Accumulating evidence confirmed that glutaminase was closely related to tumor cell growth and proliferation." (PMID 37072493, 2023). "Glutaminase (GLS), highly expressed in tumor cells, is an enzyme that breaks down glutamine into glutamate." (PMID 38264667, 2023). "Glutamine uptake inhibitors(V-9302), glutamine antimetabolites(L-DON/JHU-083), and glutaminase inhibitors (CB-839) are confirmed to be effective in reshaping glutamine metabolism in immune cells and function as anti-tumor immune microenvironment." (PMID 37635935, 2023). "Inhibitors of glycolysis and glutamine metabolism enzymes, such as 2-deoxyglucose (2-DG) and glutaminase inhibitors, are being investigated for their potential to disrupt tumor metabolism and inhibit tumor growth." (PMID 37626657, 2023). "Glutamate, obtained from glutamine by glutaminase conversion, is indispensable for tumor cells because of its role as a forerunner to produce α-KG, which further generates carbon and nitrogen in the tumor cells." (PMID 37446288, 2023). "In the process of energy acquisition by tumor cells, several key enzymes are involved in the reaction, such as glutaminase (elevated expression in several tumor tissues), IDO, and AMP-activated protein kinase." (PMID 37055849, 2023). "Blocking single glutamine transporters during importing into tumor cells or inhibiting glutaminase can prevent the growth and proliferation of tumor cells." (PMID 36721212, 2023). "Because of the critical role of glutamine, the inhibition of GLS activity is a potential target for tumor therapy." (PMID 37848492, 2023). "The decrease in glutamine was of particular interest, as pharmacological blockade of glutamine metabolism in tumour-bearing mice or glutaminase deletion in tumour cells suppresses cancer cell growth and enhances CD8+ T cell anti-tumour activity." (PMID 37407815, 2023). "Out of the identified regulators, six genes (SLC6A3, MITD1, CCS, LIPT2, ATOX1, and GLS) showed increased expression in tumor tissues, while PDHB had higher expression in normal tissues." (PMID 38159255, 2023). "Genes such as ARF1, SLC25A5, and CDKN2A were significantly up-regulated in tumor samples, while genes such as SNCA, PRNP, and GLS were significantly down-regulated in tumor samples." (PMID 36980514, 2023). "In this regard, several studies in a broad variety of tumor entities have shown synergistic effects of glutaminase inhibitors with frequently used cytostatics." (PMID 37255933, 2023). "Glutaminase, a vital enzyme for glutamine metabolism, is specifically deleted from tumor cells, which boosts T cell activation and improves anti-tumor immune responses." (PMID 38292487, 2023). "The results show a significant increase in the expression of SLC3A3, MITD1, LIPT2, ATOX1, PDHB, and GLS in tumor tissues compared to normal esophageal tissues." (PMID 38159255, 2023). "CB-839 showed an acceptable safety profile, significant glutaminase inhibition, and preliminary signs of clinical activity in multiple tumor types." (PMID 36959802, 2023). "Another GLS inhibitor, CB-839 inhibits the conversion of glutamine to glutamate and thereby restricts tumor proliferation in non-small-cell lung cancer." (PMID 37367892, 2023).
tumor (continued). "Conversely, both protein and mRNA levels of glutaminase (GLS) 2 display negatively associated with late stage, vascular invasion, tumor relapse, overall survival, and disease-free survival." (PMID 37635935, 2023). "After prolonged GLS inhibition, the tumor showed compensatory glutamine metabolism and growth recovery." (PMID 37924140, 2023). "For instance, the expression levels of GLS showed the largest inter-tumor heterogeneity, with some tumors having very low levels of GLS (KICH, UCEC, LUSC and KIRC), while CHOL had a clearly high level of GLS expression." (PMID 36647100, 2023). "The GNA14 expression level was found to be higher in the adjacent tissues than in the tumor tissues, whereas GLS and MEX3B expression was lower in the adjacent normal tissues." (PMID 38304027, 2023). "The Nrf-2-driven metabolic state renders recurrent tumour cells sensitive to glutaminase inhibition, which prevents reactivation of dormant tumour cells in vitro." (PMID 36701089, 2023). "In a study on mouse TNBC model, T effectors and tumor cells compete for glutamine from the microenvironment; deletion of glutaminase in tumor cells, an enzyme crucial for glutamine metabolism, activates T cells and enhances antitumor immune responses." (PMID 36624636, 2023). "Under oxidative stress, SUCLA2 increases glutamine catabolism and the production of nicotinamide adenine dinucleotide phosphate as well as glutathione by activating GLS, thereby ameliorating oxidative stress and promoting tumor growth." (PMID 38062233, 2023). "The hypermethylation of the BCAT1 promoter inhibits the BCAT1 gene, and the decrease in the expression of BCAT1 reduces the supply of glutamate, increases the dependence on glutaminase, and reduces tumor proliferation and invasion." (PMID 38028625, 2023). "Other drugs with tumor-starving effects, such as glutaminase inhibitors and glucose transporter inhibitors, have also been reported to exert inhibitory effects on the stroma." (PMID 36900176, 2023). "The high ratio of phosphoribosyl pyrophosphate amidotransferase (PPAT) to glutaminase (GLS1) enhances tumor growth including SCLC." (PMID 36597133, 2023). "Recurrent tumours with high NRF2 activation were sensitive to glutaminase inhibition, therefore presenting a potentially novel therapeutic strategy for treating recurrent tumours by controlling relapse after therapy." (PMID 35715635, 2022). "The glutaminase (GLS), a critical enzyme responsible for the conversion of glutamine to glutamate, plays an essential role in the tumor cell metabolism, growth, and proliferation." (PMID 35581670, 2022). "Unexpectedly, adjacent liver tissue had more GLS1 expression than tumours, whereas the liver type glutaminase GLS2 was slightly increased in tumours compared with adjacent tissues." (PMID 35538890, 2022). "In head and neck squamous cell carcinoma, inhibition of GLS activity with the glutamine antagonist DON resulted in decreased tumor sphere formation and abrogation of stemness properties." (PMID 36499623, 2022). "Glutaminase, specifically glutaminase 1 (GLS1) expressed in mitochondria, converts glutamine to glutamate, but also stimulates the growth of tumour cells and is involved in autophagy, signal transduction, and radioresistance." (PMID 36144335, 2022). "We found that tumor-infiltrating T cells had the highest expression of glutaminase, ribosomal protein 37, and cystathionine gamma-lyase in NSCLC, highlighting the metabolic flexibility of this cell type." (PMID 35087143, 2022). "The tumor sphere formation ability was also significantly reduced by CB-839 or compound 968, suggesting a potential utility of GLS inhibitors in TNBC." (PMID 36499623, 2022). "We then analysed the correlation of tumour glutaminase activity with the expression of GLS1, GLS2, GCN5L1, c‐Myc and two major glutamine transporters downstream of c‐Myc, which are known to activate mTORC1 in HCC specimens." (PMID 35538890, 2022).
tumor (continued). "On the other hand, LF tumours displayed suppressed expression of GLS and GLUD1, referring a decreased glutaminolysis to enter into TCA cycle for mitochondria oxidative bioenergetics." (PMID 36615660, 2022). "In the single-cell dataset, we observed the highest expression of glutaminase in tumor-infiltrating T cells as compared to all other major cell types, suggesting interesting regulatory effects related to glucose and glutamine in T cells and tumor cells." (PMID 35087143, 2022). "Glutaminase catalyzes the breakdown of glutamine in mitochondria and regulates oxidative phosphorylation, redox state, and cellular metabolism to promote tumor growth." (PMID 36818726, 2022). "At the same time, tumours had greater elevations in glutaminase activity than the adjacent liver tissues." (PMID 35538890, 2022). "GLS encodes glutaminase which functions as a substrate of MET kinase and energizes tumor migration via the Warburg effect." (PMID 36003780, 2022). "Telaglenastat (CB-839) is a potent orally bioavailable GLS inhibitor that has exhibited anti-tumor activity in breast cancer and lymphoma." (PMID 36276057, 2022). "We found that LIAS and CDKN2A were significantly upregulated in tumor samples, and FDX1, DLD, DLAT, PDHA1, PDHB, MTF1, and GLS were significantly downregulated in tumor samples." (PMID 36531222, 2022). "Unfortunately, however, the therapeutic efficacy of glutaminase inhibition in Myc-driven tumours is rarely observed in vivo." (PMID 35945217, 2022). "demonstrates that the inhibition of glutaminase with telaglenastat improved the tumor-killing capacity of autologous patient-derived T cells against melanoma." (PMID 36713558, 2022). "Further metabolomic analyses revealed that tumor cells that survived after glutaminase inhibition depend on glycolysis and glycogen synthesis for energy production." (PMID 36499623, 2022). "Although as a single-agent CB-839 has limited efficacy, our results indicate that targeting endothelial GLS genetically leads to tumor vessel normalization and increased drug delivery." (PMID 36381236, 2022). "Glutamine is processed by glutaminase, a mitochondrial enzyme active in tumours, producing glutamate and α-ketoglutarate, which then progress to produce carbon and nitrogen for the biosynthesis of proteins, FA and nucleic acids." (PMID 35715635, 2022). "BPTES and 968, are the two major classes of GLS inhibitors that have been shown to have anti-tumor activity." (PMID 35897036, 2022). "Here, we assessed if targeting GLS in vascular ECs affects pathologic angiogenesis, tumor blood vessel structure and function, and tumorigenesis and metastasis, as GLS2 is expressed at low level in ECs." (PMID 36381236, 2022). "Glutaminase 1 (GLS1), as a mitochondrial enzyme, is required for metabolizing glutamate and ammonia from glutamine and its activity has been shown to be upregulated in tumor cells compared to normal cells." (PMID 35628289, 2022). "Studies have shown that glutaminolysis can be controlled by glutaminase succinylation, leading to the inhibition of tumor growth." (PMID 35515122, 2022). "ALDH18A1 and glutaminase protein are highly expressed in proliferative estrogen receptor positive (ER+) tumor cells compared to ER− cells." (PMID 35169275, 2022). "Collectively, GCN5L1 functions as a tumour regulator by modulating glutaminase acetylation and activity in the development of HCC." (PMID 35538890, 2022). "Of the six cuprotosis-related genes included in the signature, we found FDX1, LIAS, DLAT, MTF1, and GLS to be differentially expressed between tumor and normal tissues at the protein level." (PMID 36247012, 2022).
tumor (continued). "For other metabolic inhibitors, such as the glutaminase inhibitor telaglenastat, surrogate genetic biomarkers leading to tumor glutamine dependence are being employed (e.g., NRF2/KEAP1)." (PMID 34981784, 2022). "For example, glutaminase inhibition blocks the reactivation of dormant tumor cells and prevents recurrent tumor cell growth." (PMID 35158815, 2022). "Consistently, mouse studies showed that expression of SUCLA2 S79A or GLS K311R significant inhibited tumor growth and reduced the levels of GSH/GSSG ratios in tumor tissues." (PMID 34913133, 2022). "Tumor cells-specific deletion of glutaminase, a critical enzyme for glutamine metabolism, promotes T cell activation and enhances antineoplastic immune responses." (PMID 35062950, 2022). "Several studies had confirmed that when GULT or glutaminase inhibitors were used on tumor cells with high expression of SLC7A11, the mortality of tumor cells was significantly increased, and this effect was independent of the GSH-GPX4 axis." (PMID 36457488, 2022). "Tumor cells increased the metabolism of glutamine by adding GLS, thus providing energy for the growth of tumor cells." (PMID 35359580, 2022). "The synergism of mTOR and different metabolic inhibitors has been described in several tumor types, including CCRCCs, in which the combination of everolimus and GLS inhibitor (CB-839) was also tested." (PMID 36142502, 2022). "Of the six cuprotosis-related genes, we found that FDX1, LIAS, DLAT, MTF1, and GLS were differentially expressed between tumor and normal tissue and were upregulated in normal tissue." (PMID 36247012, 2022). "In fact, Glutaminase (GLS) inhibitors, such as CB-839, an orally available, potent, and specific inhibitor of GLS, have shown anti-tumor efficacy." (PMID 35326714, 2022). "Other compounds such as V-9302, a selective ASCT2 inhibitor, or CB-839, a glutaminase inhibitor, have also been tested in preclinical models resulting in an amelioration of anti-tumour immunity and subsequent enhanced tumour control." (PMID 34637000, 2021). "On the other hand, the interference with glutaminolysis by inhibiting glutaminase (GLS1) activity was similarly effective in blunting the immunosuppressive phenotype of macrophages, tumor-associated immature myeloid cells and MDSCs." (PMID 34831183, 2021). "Tumor cells use the enzyme glutaminase to convert glutamine to glutamate and to produce precursors for the glutathione synthesis pathway, as well as using it in fatty acid production, which stimulates tumorigenesis." (PMID 34564447, 2021). "c-Myc is known as an important driver in maintaining a glutaminolysis phenotype, particularly in ER- tumours, and enhances GLS activity indirectly via suppressing the expression of miR-23a/b." (PMID 34439127, 2021). "PTC cells generate glutamate through glutaminase and glutamate dehydrogenase, whereby glutamate further produces α-ketoglutarate, which provides sufficient energy for the survival of tumor cells." (PMID 33598460, 2021). "The expression of an antisense lncRNA of glutaminase (GLS-AS) can be suppressed in some tumor types, and this correlates with high levels of glutaminase." (PMID 34440124, 2021). "There was a trend towards higher GLS protein expression in the high proliferative luminal tumours compared with the low proliferative tumours (p = 0.051)." (PMID 34439127, 2021). "Accordingly, glutaminase (GLS) inhibitors blocked UPS tumor growth in vivo and are the object of clinical trials in humans." (PMID 34294128, 2021). "Among these is GLUD1, which was weakly associated with GLS and GLS2 at both mRNA and protein levels in the low and high proliferative tumours." (PMID 34439127, 2021). "More importantly, ZBTB7C can also regulate tumor glutamine metabolism by affecting the transcription of glutaminase (GLS1)." (PMID 33946045, 2021).